RNU6-315P (RNA, U6 small nuclear 315, pseudogene)
Gene: Small nuclear RNA gene on chromosome 3 (170,149,845 to 170,149,951, forward strand). Ensembl gene ENSG00000199536.
Homologues: Orthologues: chimpanzee U6 (99% identical), macaque U6 (93% identical), guinea pig U6 (80% identical), dog U6 (79% identical). Paralogues in human: RNU6-38P (88% identical), RNU6-15P (87% identical), RNU6-25P (87% identical), RNU6-574P (87% identical), RNU6-1 (86% identical), RNU6-1011P (86% identical), RNU6-1060P (86% identical), RNU6-116P (86% identical), RNU6-166P (86% identical), RNU6-2 (86% identical), RNU6-27P (86% identical), RNU6-33P (86% identical), and 1292 more.